PNPLA2 (patatin like domain 2, triacylglycerol lipase)
Diseases named in the same sentence as PNPLA2 in open-access papers (continued):
Sharing a sentence is not in itself a finding about the gene and the disease.
tumor (95 papers, 2014 to 2026). "We also investigated the association of the LM.Sig with clinical information, and the results showed that gene PNPLA2 correlated with advanced tumor progression and adverse prognosis, while the other six genes exhibited the opposite trend." (PMID 40568577, 2025). "Although PNPLA2 has been recognized as a downstream effector of ABHD5, it remains unclear whether ABHD5 exerts its tumor-suppressive functions exclusively through PNPLA2-mediated lipolysis." (PMID 41349769, 2025). "Interestingly, PNPLA2 was positively correlated with stromal and immune score, and was negatively correlated with tumor purity." (PMID 40568577, 2025). "Glycerol can also be externally provided to tumor cells by PCa adipose tissue, as adipocytes treated with PCa-conditioned media increase their levels of PNPLA2 and secrete large amounts of free glycerol that may enter the PCa cells, fueling lipid metabolism." (PMID 34572917, 2021). "Interestingly, when we tested PNPLA2 expression in WD and DD components of the same tumor, the expression was lost in both." (PMID 32158531, 2020). "Although we witnessed blunted reductions when compared with sham animals in genes such as Lipe, Plin1, Pnpla2, and Fasn in tumour mice treated with ACVR2B/Fc compared untreated tumour mice, there were not statistically significant differences between the two tumour groups." (PMID 33200567, 2020). "Indeed, tumor progression is accelerated by reduced activity of adipose triglyceride lipase (ATGL, formally PNPLA2), the rate-limiting TG lipase, or loss of αβ hydrolase domain containing 5 (ABHD5), the essential coactivator of ATGL." (PMID 33219129, 2021). "Moreover, the significantly lower level of PNPLA2 is associated with R1 surgical margins, compare to R0 margins, which suggests the more invasive tumor phenotype in the absence of PNPLA2." (PMID 32158531, 2020). "ATP5B and PNPLA2 PEDF receptors on macrophages and CD47 on tumor cells were respectively up- and down-regulated by PEDF." (PMID 28403150, 2017). "PEDF receptors (ATP5B, PNPLA2, and LRP6) and CD47 mRNA and protein expression were quantified in macrophages and tumor cells by quantitative RT-PCR, western blot, immunofluorescence and flow cytometry." (PMID 28403150, 2017). "To go one step further in our study, we are now proposing to optimize the CRISPR-Cas9 genome editing technology to knock-out CD47, PNPLA2 and ATP5B in tumor and macrophage cells." (PMID 28403150, 2017). "Moreover, PNPLA2 showed an overexpression in normal tissues than that in tumor tissues, whereas all the other genes, except LIPT1, were up-regulated in the tumor tissues." (PMID 40568577, 2025). "Thus, our data illustrated a novel PEDF-mediated signaling involving PNPLA2 up-regulation on macrophages to induce M1 polarization and, CD47 down-regulation on tumor cells which in collaboration with ATP5B elevation on macrophages leads to phagocytosis." (PMID 28403150, 2017). "As expected, our data showed that both S-BEL and Atglistatin treatments inhibited macrophage differentiation without affecting phagocytosis therefore validating PNPLA2 role in tumor cell differentiation." (PMID 28403150, 2017). "Notably, PNPLA2 knockout failed to phenocopy these effects, indicating that the tumor-suppressive function of ABHD5 is independent of its canonical lipolytic role." (PMID 41349769, 2025). "In addition, these CENPF-related genes exhibited the expression differences between normal and tumor tissues: the expression of TOP2A or KIF23 was significantly upregulated in LPS, while that of BAG1,PNPLA2, CRYL1 or GRN was significantly downregulated in LPS or MRCLPS compared to normal tissues." (PMID 37108172, 2023). "There are also no studies that clearly describe the regulation of Pnpla2 in tumor cells." (PMID 35912266, 2022).
tumor (continued). "While the combination of PNPLA2 inhibitors and Angiostatin was toxic and did not allow us to analyze their combined effects on macrophage differentiation and phagocytosis, we investigated the relative role of CD47 and ATP5B in tumor cell phagocytosis." (PMID 28403150, 2017).
myopathy (35 papers, 2008 to 2026). A disease of the muscle in which the muscle fibers do not function properly. "The case highlights two severe PNPLA2 mutations leading to complete ATGL deficiency and an unusual early-onset myopathy in childhood." (PMID 40919432, 2025). "Janssen also described heterozygous PNPLA2 mutation in the patients showing neutral lipid storage in muscle, Jordan’s anomaly and myopathy." (PMID 31655616, 2019). "This is an intriguing case, displaying severe PNPLA2 mutations with clinical presentation characterized by slight cardiac impairment and full expression of severe asymmetric myopathy." (PMID 28258942, 2017). "In conclusion, we describe a 54-year-old NLSDM female patient showing late onset myopathy in association with slight cardiac involvement, although the identified novel mutations completely abrogate PNPLA2 protein function." (PMID 28258942, 2017). "Pnpla2 encodes a lipase that hydrolyzes fatty acids from triacylglycerol and mutations of the gene produce a myopathy." (PMID 27891095, 2016). "Rare mutations in the PNPLA2 gene, resulting in a truncated protein with no capacity to bind to lipid droplets but with an intact patatin domain, has been identified in a subgroup of patients with neutral lipid storage disorder (NLSD) with mild myopathy." (PMID 19390624, 2009).
infection (15 papers, 2014 to 2025). The state of being infected such as from the introduction of a foreign agent such as serum, vaccine, antigenic substance or organism. "In particular, we established that host Pnpla2 involved in neutral lipid mobilization is dispensable for P. berghei LS infection in MBA-differentiated mouse ESCs." (PMID 32442532, 2020). "Discrepancy in infection phenotype between PNPLA2 siRNA knockdown and Pnpla2 gene knockout could be due to off-target effects of siRNAs leading to false positive hits thus requiring validation in a gene knockout system." (PMID 32442532, 2020). "NR1D2-mediated PNPLA2/ATGL inhibition disrupts the lipid metabolism of macrophages in the human body, leading to lipid accumulation and weakening the effect of autophagy on Burkholderia pseudomallei immunity to infection, leading to the continued development of infection." (PMID 34925055, 2021).
inflammation (1 paper, 2022). Aberrant reaction of the microcirculation characterized by movement of fluid and leukocytes from the blood into extravascular tissues. "Furthermore, the PNPLA2-deficient mouse has been shown to suffer from hepatic inflammation and the development of atherosclerotic lesions, highlighting an anti-inflammatory role of PNPLA2 stimulated by PEDF." (PMID 36201200, 2022).
neurodevelopmental disorder (1 paper, 2023). A behavioral and cognitive disorder with onset during the developmental period that involves impaired or aberrant development of intellectual, motor, or social functions. "For example, all TRSs associated with ADHD include three genes, PNPLA2, PLK1S1 and GMPPB, previously associated with ADHD and/or other neurodevelopmental disorders." (PMID 37537283, 2023).
PNPLA2 also shares sentences with these, for which no sentence is quoted: metabolic disorders (17 papers); metabolic syndrome (14); lung carcinoma (13); atherosclerosis (10); hyperlipidemia (10); colorectal cancer (8); cardiac hypertrophy (7); Chanarin-Dorfman syndrome (7); colon cancer (6); liver cancer (6); Glucose intolerance (5); Hyperglycemia (5); lung adenocarcinoma (5); melanoma (5); ovarian carcinoma (5); cardiovascular disease (4); coronary artery disease (4); Hepatic fibrosis (4); Hyperinsulinemia (4); hypertriglyceridemia (4); keratoconus (4); pancreatic adenocarcinoma (4); cervical cancer (3); endothelial dysfunction (3); gastric cancer (3); genetic disorder (3); gestational diabetes mellitus (3); heart disease (3); Lewis lung carcinoma (3); lipodystrophy (3).
A further 114 diseases each share a sentence with PNPLA2 in 3 papers or fewer.